MMP1 (matrix metallopeptidase 1)
Diseases named in the same sentence as MMP1 in open-access papers (continued):
Sharing a sentence is not in itself a finding about the gene and the disease.
tumor (continued). "Although all keratinocytes responded very similarly to vemurafenib in their expression profile, particularly with a significant induction of MMP1 and MMP3, only the HrasA5 cells revealed a vemurafenib-dependent pathophysiological shift to tumor progression, i.e., the initiation of invasive growth." (PMID 35174094, 2022). "It indicates that MMP1 may have a similar role to MMP3, acting only in the initial stage of tumor metastasis and appearing to be less important once metastasis occurs." (PMID 36338624, 2022). "MMP1 and MMP10 mainly affect the migration, invasion and angiogenesis of tumour cells." (PMID 35501390, 2022). "MMP-1 and ADAMTS-1 proteolytically release EGF-like ligands, including amphiregulin (AREG), heparin-binding EGF (HB-EGF), and transforming growth factor α (TGF α), from tumor cells." (PMID 36338393, 2022). "We also found no statistical differences in the protein levels of MMP1 from most tumor types, which should be related to the fact that protein expression is regulated at multiple levels." (PMID 36727076, 2022). "In fact, MMP1 is upregulated in most cancer tissues, regardless of the prevalence of cachexia in the specific tumour types." (PMID 36428623, 2022). "Furthermore, CAFs secrete MMP-1, MMP-3, MMP-7, MMP-9, and MMP-13, releasing ECM-bound growth factors such as VEGF supporting tumor angiogenesis." (PMID 35572966, 2022). "These reported significantly higher concentrations of mainly MMP-1, MMP-2, MMP-3 and MMP-9, but also of other MMPs in the saliva of patients with OSCC, compared to healthy controls, which were also correlated with the tumor stage." (PMID 36547091, 2022). "In addition, UALCAN database was used to confirm that protein levels of MMP1 were higher in COAD, HNSC, PAAD, and LUAD tumor tissues than in corresponding controls." (PMID 36727076, 2022). "In addition, MMP1, MMP2 and MMP9, which are closely related to tumor cell migration, were significantly upregulated in the GDF10‐treated group." (PMID 33657265, 2022). "In this sense, we also acknowledge that potential dysregulation of inflammation-related genes included in our proposed molecular signature (e.g., IL1A, MCM2, MMP1, MMP12, and VEGFA) might be due to the inflammation favoring tumor maintenance and progression." (PMID 34638231, 2021). "Our results show that only the expression of MMP-1 and MMP-3 in tumor tissue could be related to the progression of BC and suggest prioritizing these MMPs as candidates for development of therapeutic strategies in these patients." (PMID 34445715, 2021). "This spatial heterogeneity might determine the accumulation of MMP1 and the activation of FAK at the tumor front." (PMID 33513131, 2021). "Furthermore, it is shown that hAMSCs increase the expression of MMP-1 and reduce the ratio of TIMP-1/MMP-1, which participates in tumor neovascularization, and subsequent metastasis." (PMID 33579346, 2021). "These HLA-A24 ligands were possibly overexpressed in tumor samples and were therefore chosen as nonmutated TAA candidates of CRC111, which comprised peptides encoded by the KLK8, DEFA3, STRIP2, MMP1, FSCN1, TBX15, and PHLDA1 genes." (PMID 34185709, 2021). "Two variants were found exclusively in cell 2 and not in its tumor (MMP1 and STAT3), whereas two variants were found only in the tumor from which cell 6 was derived (ERBB2 and MLH3)." (PMID 33917394, 2021). "Of the studied population of women (controls-cases), not all of them presented immunohistochemical expression of MMP-1-2-3-9 (percentage-intensity) in the mammary tissue analyzed with and without tumor disease." (PMID 34445715, 2021). "Our results show a significantly higher mRNA expression of MMP1, MMP9, POSTN, GREM1, FMOD, and COL1A2 in tumor biopsies compared to normal tissue, but the significant difference between responder and non-responder groups was only found for the expression of FMOD mRNA." (PMID 34283070, 2021).
tumor (continued). "Additionally, interstitial-space–related genes, such as matrix metalloproteinase 1 (MMP1), MMP9, cathepsin, and zinc finger-binding homeobox 1 (ZEB1), play an important part in tumor metastasis." (PMID 33842351, 2021). "The present study shows that there is a statistically significant association between the immunohistochemical expression of MMP-1 and MMP-3 in the breast tissue of women suffering BC and their expression in the tissue of patients without tumor disease." (PMID 34445715, 2021). "Among them, MMP-1, MMP-2, and MMP-9 are closely related to tumor invasion and metastasis." (PMID 35280249, 2021). "Next, we used ImmuCellAI to evaluate the immune infiltration score and the abundance of 24 immune cells from tumor tissues, and then calculated the multiple and single correlation coefficients of ADAM12, MMP1, SERPINE1, PLOD3, and P4HA3 with mRNA expression and immune infiltration score." (PMID 34121340, 2021). "Numerous signaling molecules, including stromal derived factor-1 (SDF-1/CXCL12), transforming growth factor-β (TGF-β), interleukin-8 (IL-8), matrix metalloproteinase-1 (MMP-1), and monocyte chemoattractant protein 1 (MCP-1/CCL2) were shown to be involved in MSC recruitment to the primary tumor site." (PMID 33287630, 2021). "Co-culturing HepG2 and Huh7-tumor cells with LX2-cells in the transwell assays significantly increased mRNA-expression of the pro-metastatic marker MMP9 in HepG2-cells and MMP1 in HepG2 and Huh7-cells." (PMID 33103995, 2020). "Furthermore, depletion of NOX4, ANGPTL4, MMP-1, and MMP-9 in CRC cells significantly blocked OA-enhanced metastatic seeding of tumor cells in lungs." (PMID 32641980, 2020). "Matrix metallopeptidase 1 (MMP1) is a key enzyme that promotes the breakdown of extracellular matrix during physiological and pathological processes such as embryonic development, reproduction, and tissue remodeling, as well as tumor invasion and metastasis." (PMID 32299427, 2020). "Cannabinoids also curtail tumor invasion and metastasis by inhibiting the secretion of matrix metalloproteinase (MMP)-2 and MMP-9, while increasing the tissue inhibitors of MMP-1 (TIMP-1)." (PMID 33066359, 2020). "A slightly increased expression of MMP1 was observed in the NSCLC-without-IPF tumor tissue and the IPF tissue compared with the adjacent normal lung tissue sections or with the healthy donor lung tissue." (PMID 33046043, 2020). "Therefore, inhibiting expression of MMP-1, which is used as a major marker of UVB-induced skin photoaging, is crucial for skin collagen preservation." (PMID 32522955, 2020). "MMP1 expression was mostly observed in the alveolar epithelium in the IPF tissue; whereas in the NSCLC-without-IPF tumor tissue, MMP1 presented predominantly in the glandular epithelium." (PMID 33046043, 2020). "Interestingly, tumor cells displayed distinct MMP secretion profiles according to their invasive properties and target vasculatures: hematogenous cells secreted MMP-1, -2, -3, and -10 while lymphogenous cells secreted MMP-1, -2, and -9." (PMID 33224956, 2020). "Hence we validated gene expression of MMP1, MMP3, MMP11, MMP13, MMP14, ADAMTS1 and ADAMTS5 genes belonging to metallopeptidase activity, using qPCR in 67 tumours." (PMID 31292488, 2019). "Whilst the molecular basis for this requires further experimentation it is interesting that MMP1 and MMP13 have been found to be upregulated in a variety of different tumours, including cervical, whilst MMP8 on the other hand has been associated with an anti-invasive effect in certain settings." (PMID 31116803, 2019). "In conclusion, we observed increasing recruitment of VEGFR1+CD133+ HPCs to the lung during tumor metastasis and found high expression of CXCL-16, IL-2Rα, IL-2Rγ, MMP-1, MMP-9, PDGFR-α, SDF-1α, TGF-β, PECAM-1, and VE-cadherin in highly metastatic MDA-MB-435s cells." (PMID 30483898, 2019).
tumor (continued). "HIF proteins induce the expression of several genes involved in tumor phenotypes, such as platelet-derived growth factor (PDGF), transforming growth factor alpha and beta (TGF-α, TGF-β), matrix metallopeptidase 1 (MMP1), C-X-C chemokine receptor type 4 (CXCR4)." (PMID 30708988, 2019). "Importantly, we show that Mmp-1 induction and then JNK pathway activation are still present in tumour from larvae devoided of Defensin." (PMID 31358113, 2019). "MMP1-immunostaining of tissue sections yielded a diffuse cytoplasmic signal that was neither tumour- nor cell differentiation-specific and, therefore, was non-discriminatory (not shown)." (PMID 31640696, 2019). "In a recent study comparing the matrsiome of MDA-WT and MDA-Lung tumour xenografts, MMP1 and THBS2 were detected uniquely in MDA-WT tumours and AGRN was detected uniquely in MDA-Lung tumours, which correlates with our proteomics data of MDA-WT and MDA-Lung secretomes." (PMID 31160380, 2019). "In addition, proteins involved in tumor cells invasion such as CXCL1, CXCL5, and MMP1 were displayed to be expressed and interacted with ICAM-1 and TGFβ2 in the network analysis." (PMID 29966014, 2018). "In agreement with the role of FGFR1 in promoting cell proliferation and carcinogenesis, a number of iFGFR1-upregulated genes are cancer-driving genes such as ETS1, PIM1, NRG1, MMP1, and FOXQ1, while some iFGFR1-downregulated genes are tumor suppressors such as NR4A1 and GDF15." (PMID 30111373, 2018). "MMP-1 was expressed in tumour-free peritoneum and in the invasion zone between tumour and peritoneal tissue, but not in tumour-invaded areas." (PMID 29623449, 2018). "Taken together, these results demonstrated that MMP‐1 secreted by MSCs could efficiently cleave the IGF‐2/IGFBP2 complex, facilitating the migration of MSCs toward tumor cells via the IGF‐2/IGF‐1R signaling axis." (PMID 29321953, 2018). "Indeed, both MMP1 and its inhibitor TIMP1 (tissue inhibitor of metalloproteinases 1) are members of a well-characterized class of proteinases involved in tumor invasiveness and cancer metastases." (PMID 29420626, 2018). "In the present study, the expression of MMP-1 was generally seen in tumour-free peritoneum and not peritoneum invaded by tumour." (PMID 29623449, 2018). "Together with increasing production of MMP1 and enhancing motility, TRIM44 may promote tumor invasion and metastasis." (PMID 28885545, 2017). "Moreover, GM6001 mostly inhibits the activity of secreted MMP-1, 2, 3, 7, 8, 9 and 12 and almost completely prevents the shedding of MICA/B at the surface of tumor cells treated with the CAFs CMs, suggesting that one or several of these MMPs are involved." (PMID 28423623, 2017). "Firstly, by combininginteracting with integrin alpha6beta1, CD 147 take part in FAK P13K-Ca (2+) and MARK signal pathway, interstitial collagenase (MMP-1) is producted and CD147-MMP-1 complex is formed at the tumor cell surface, thus modifying the tumor cell pericellular matrix to promote invasion." (PMID 28881651, 2017). "Besides, matrix metalloproteinase-1 (MMP-1), one of the main enzymes involved in ECM degradation, was increased expressed in the tumor tissues of HF- and MCD-fed mice." (PMID 29221151, 2017). "Furthermore, circulating tumor cells derived from TNBC-bearing mice display increased levels of FRA-1 and MMP-1 compared with parental cells, supporting a role for the MLK3–FRA-1–MMP-1 signaling axis in vascular intravasation." (PMID 28604765, 2017). "In addition, a not statistically significant but rather a numeric tendency of diminished expression in metastatic ganglia is apparent when MMP-1 and PAI-1 were analyzed by comparison with the expression of the primary tumor cells." (PMID 27975070, 2016).
tumor (continued). "As MMP14 is tethered to the cell surface and therefore is restricted to the proximal microenvironment, increased secretion of MMP1 by oncogenic cells may provide a mechanism to regulate cells and ECM proteins at sites distal to the developing tumour." (PMID 27324842, 2016). "Additionally, treatment with sorafenib largely blunted the transcriptional activities of MMP1 and MMP3 (p < 0.05), which are required to mediate cell invasion during wound repair and even tumor metastasis." (PMID 27339758, 2016). "The expression of MMP-1 is significantly enhanced by fibroblasts at the invasive front of BCC, suggesting its role in the initial steps of tumor proliferation, which is mediated by cleaving the ECM proteins and active forms of growth factors that subsequently stimulate cancer cells." (PMID 27271600, 2016). "Hence, the process of tumor cell invasion requires a combination of PAR-1 activity and MMP-1 expression, both of which are responsible for the collagenolytic function." (PMID 27271600, 2016). "MDCK cells did not establish a viable xenograft, however, tumour growth curves indicate that MMP1 silencing significantly reduced xenograft size." (PMID 27324842, 2016). "Moreover, MMP-10 up-regulates several other MMPs such as MMP-1, MMP-7, MMP-9, and MMP-13 that are essential for tumor progression." (PMID 27271600, 2016). "Thus, we observed expression of matrix metalloproteinases (MMP)-1, MMP-2, MMP-3, and MMP-9 mainly in the nuclei of tumor cells, while for MMP-3 and MMP-9 the immunoreactivity was also present in the cytoplasm of tumor cells and in the amyloid deposits." (PMID 27871286, 2016). "Moreover, our findings also implicate the release of MMP1-derived LAMA5 fragments with bioactive activity, into the tumour microenvironment." (PMID 27324842, 2016). "MMP1, IL24 and CCL20 are mRNAs that are well studied for their role in cancer; however the remaining mRNAs have not been characterized for their potential role in HNSCC tumorigenesis and/or tumor progression and warrant further study." (PMID 26498364, 2015). "Further studies on MMP-1 involvement in EMT may reveal and important mechanistic step in the development of tumor cells metastatic potential." (PMID 25664615, 2015). "It is to be noted that the MMP1 collagenase expression present in NHF (data not shown) was not detectable in tumour cells." (PMID 26284589, 2015). "Inactivating the JNK pathway by expressing a dominant-negative form of JNK (basket, bsk), depleting Mmp2 (but not Mmp1) or expressing the tissue inhibitor of metalloprotease (timp) in EBs of Sox21a flies reduced tumour burden and growth towards the lumen." (PMID 26690827, 2015). "Similarly, CXCL5, CXCL13, CCL1, CCL7 and CCL26 in WF collected from patients with T1–2 tumor tend to be higher than those with Tis, and the profiles of CXCL13, CCL27, MMP-1 and MMP-7 in WF from N1–3 patients tend to be higher than those with N0." (PMID 26313265, 2015). "We suppose that the therapeutical targeting of MMP1 could lead to decreased MMP1-induced EMT and subsequently, to decrease of CTC_EMT, with implications for tumor dissemination and treatment resistance." (PMID 24972610, 2014). "In our study, both MMP-1 and MMP-13 expression was observed in all three cell types studied (tumor cells, fibroblasts, and MICs), but we only found a significant correlation between MMP-1 and MMP-13 positive expression and high Pit-1 levels in tumor cells and fibroblasts." (PMID 25527274, 2014). "As Rabex-5 and Rbpn-5 mutants both show upregulation of the JNK target gene Mmp1, it appeared likely that ectopic activation of the JNK pathway could also be contributing to tumour formation." (PMID 24104056, 2014). "Strong upregulation of Mmp1 levels was also seen, particularly in non-differentiated regions of the disc, indicating that tumours are likely to possess metastatic ability." (PMID 24104056, 2014).
tumor (continued). "MMP-10 (also known as stromelysin 2) is generally limited to epithelial cells and can target pro-MMP-1, -7, -8, -9, -13, collagen type III, IV, V, gelatin, elastin, fibronectin, proteoglycans and laminin, activities that have been shown to promote tumor cell invasion." (PMID 24885595, 2014). "In humans, this protein was first described by Biswas and colleagues as a tumor cell-derived collagenase-stimulatory factor termed TCSF made by tumour cells that stimulates production of a collagenase (matrix metalloproteinase type 1, MMP-1) by fibroblasts." (PMID 25580061, 2014). "In order to explore whether knockdown of each of these MMPs could also modify the metastatic potential of Pit-1-overexpressing MCF-7 cells in vivo, we evaluated the effect of MMP-1 and MMP-13 knockdown in an SCID mice tumor xenograft model." (PMID 25527274, 2014). "At day 24, considerable tumor growth was observed in controls, while almost no tumor growth was observed in MMP-1 and MMP-13 knockdown mice (data not shown)." (PMID 25527274, 2014). "We showed that tumour cells are able to down-regulate the expression of ECM genes such as type I collagen and CCN2, while up-regulating the expression of collagenases such as MMP1 in neighbouring fibroblasts." (PMID 24090133, 2013). "Interestingly, our novel findings concerning expression levels of CXCL9, IL8, MMP1, MMP3 and COL1A1 are the converse of previously reported results: CXCL9 protein can modulate host cell infiltration and tumor behavior." (PMID 23405235, 2013). "In that study conducted in Poland, MMP1 was associated with node- negative breast cancer, whereas MMP9 was associated with ER−/PR− tumors, greater lymph node involvement, and larger tumor size." (PMID 23696797, 2013). "Some of these gene nodes have been shown to be functionally involved in other cancer types, including regulation of tumor cell proliferation (Creb, C/ebp, ATF3, ATF4), invasion (MTHFD2, FGF2) and metastasis (PTGS1/COX1, E-selectin, ATF3, FGF2, IL1A, MMP1, MMP13)." (PMID 24124450, 2013). "One study hypothesized that MMP-1 was involved in local invasion and that MMP-9 was involved in tumor growth and malignancy." (PMID 23696797, 2013). "Patients with tumours expressing MMP-1 at the primary site are reported to have a significantly worse prognosis than MMP-1 negative patients." (PMID 22500976, 2012). "Nor was any association found, when basal-like and non-basal-like groups and MMP-1 expression in tumour cells or in stromal cells were analyzed." (PMID 21835023, 2011). "Stromal cell are often recruited by tumor cells via extracellular matrix metalloproteinase inducer to enhance invasion and stimulate the production of MMP-1 and MMP-2, again unlike the suppression of migration and MMPs reported here." (PMID 21637818, 2011). "Characterization of these cells during development indicates that fra mutant cells display characteristics of invasive tumor cells, including increased levels of phospho-ERK, phospho-JNK, and Mmp-1, changes in cadherin expression, remodeling of the actin cytoskeleton, and loss of polarity." (PMID 21672235, 2011). "In addition, MMP-1 and MMP-9 were found to be regulated by STAT3, which plays a crucial role in tumor invasion and metastasis." (PMID 21991388, 2011). "In-situ hybridization with an anti-sense probe demonstrates that MMP1 gene expression is detectable only in tumor cells and not in surrounding host stromal cells." (PMID 21170377, 2010). "It has furthermore been suggested that its coordinate overexpression with MMP-1 and/or MMP-2 may have a synergetic effect in tumor progression." (PMID 20946664, 2010). "In this preliminary salivary study, we confirmed that the expression of MMP1 was confined to HNSCC tumor cells as no expression was detected within the healthy population." (PMID 19835631, 2009).